EGFR (epidermal growth factor receptor)
Diseases named in the same sentence as EGFR in open-access papers (continued):
Sharing a sentence is not in itself a finding about the gene and the disease.
cancer (continued). "A subgroup of around 20–30% of patients harboring an activating mutation is intrinsically resistant to TKIs and shows weak clinical response, including those with wild-type EGFR NSCLC cancer." (PMID 36865093, 2023). "This provides an ideal environment for the activation of EGFR by the PGRMC1–heme complex to promote cancer." (PMID 37834119, 2023). "Specifically, EGFR is responsible for cancer cell survival and invasiveness under hypoxic condition." (PMID 37059730, 2023). "Amplification, overexpression, and mutation of MET and HER2 are heavily involved in EGFR TKI resistance development, and the cross talk of these receptors is a way to avoid TK inhibition in many cancers." (PMID 36865093, 2023). "BS-S, BS-SP, and BS-SPP, exhibited concentration-dependent anticancer activity in each cancer cell line with high expression of EGFR and MET receptors." (PMID 37631372, 2023). "Currently, epidermal growth factor receptor inhibitors (EGFRi) are used in the treatment of many malignant neoplasms located in head and neck, lung, large bowel, prostate, breast, ovary, stomach, and pancreas." (PMID 36990917, 2023). "EGFR is a transmembrane tyrosine kinase receptor that is overexpressed in several cancers of epithelial origin, and its natural ligands include EGF and TGF-α." (PMID 36986777, 2023). "Concomitant pemetrexed administration can retard the evolution of resistance and restore the sensitivity of cancer cells to EGFR‐TKI." (PMID 37278440, 2023). "Cross-regulation of EGFR and Wnt signaling in cancer results in abnormal increases in signaling proteins and transcription factors, leading to the failure of targeted therapies." (PMID 37841927, 2023). "Dysregulation of EGFR protein stability contributes to abnormal EGFR signaling and cancer development." (PMID 37085908, 2023). "Targeting EGFR degradation has an advantage over EGFR inhibition because it promotes a more specific interruption of Bim phosphorylation, leading to the death of cancer cells." (PMID 37754201, 2023). "We therefore studied the role of Sorcin in EGFR signaling processes, and in promoting cell proliferation, migration and invasion in cancer, and demonstrated that Sorcin acts at different levels on such processes, with a complex resulting effect." (PMID 37442828, 2023). "Using a wide-field Raman imaging system, they first showed specific in vitro binding and detection of these anti-EGFR SERS nanoprobes in cultured cancer cells overexpressing EGFR." (PMID 37998152, 2023). "EGFR inhibitors—As an important therapeutic target in cancer, the epidermal growth factor receptor (EGFR) family is often abnormally activated in many types of cancers and plays an important role in their development and progression." (PMID 37190065, 2023). "Due to its important role in cell proliferation and other cellular processes, EGFR remains an attractive target for cancer therapy including for radio- and chemo- radiosensitization." (PMID 37399454, 2023). "EGFR signaling is commonly altered in numerous human cancers due to EGFR gene amplification and/or overexpressions of protein, mutations, or in-frame deletions." (PMID 37298670, 2023). "Closely related to the EGFR/PI3K signaling pathway in cancer are mechanisms of cell cycle and proliferation regulation." (PMID 37568789, 2023). "Blocking EGFR/KRAS signals is a major goal for cancer therapy and many new therapeutic approaches are currently being designed to target EGFR/KRAS activation." (PMID 37251335, 2023). "Our study shows that EGFR knockout not only inhibits the cancer cell proliferation, invasion and migration but also dramatically prevents malignant cell fusion." (PMID 37590231, 2023).
cancer (continued). "Previously, we showed the anti-EGFR antibody nimotuzumab can be used as a positron emission tomography and fluorescent imaging probe for EGFR positive cancers in mice." (PMID 37419997, 2023). "Our work produced novel superantigen SPEA-peptide agonists and SPEA-peptide agonist-EGF conjugates for the targeted treatment of EGFR-expressing cancers." (PMID 37445686, 2023). "EGFR overexpression correlates with aggressive disease and poor prognosis, making it an optimal target for cancer therapy." (PMID 37240224, 2023). "Among the downstream genes, FN1, cadherin 2 (CDH2), EGFR, integrin subunit alpha 6 (ITGA6), and integrin subunit beta 4 (ITGB4), which are widely studied and are associated with cancer metastasis, were selected for further investigation." (PMID 37096833, 2023). "Due to the limited availability of repeated tissue biopsies, the proteomics and phosphoproteomics analysis of cancer cells with in vitro treatment of EGFR-TKI has been widely performed for the discovery of therapeutic targets and biomarkers." (PMID 36902280, 2023). "EGFR plays important roles in cancer progression, and it is one of the major drug targets for targeted cancer therapy." (PMID 36739948, 2023). "Conversely, protein degradation due to EGFR depletion results in cancer cell death, leaving fewer cells to proliferate and reducing the chance of new, resistant mutations emerging." (PMID 37754201, 2023). "Low-abundance SNV fractions of KRAS G12D, EGFR L858R, and EGFR T790M cancer markers were detected in under 2 h, and the results were validated by comparing the data with those obtained using ddPCR." (PMID 36979592, 2023). "Together, our novel findings indicate besides EGFR gene mutation, PTM of the EGFR-binding protein AnxA6 also functions pivotal roles in mediating cancer cell growth and EGFR inhibitor drug effect." (PMID 37528485, 2023). "The in vitro results indicated a specific affinity of scFv-OMVs toward EGFR overexpressed cancer cells." (PMID 37775519, 2023). "We also expressed several novel fusions in cancer cell lines and analyzed their response to EGFR and HER2 tyrosine kinase inhibitors (TKIs)." (PMID 37168365, 2023). "The subsequent suppression of STARD13 expression in weakly metastatic PC-1 cells leads to the activation of EGFR/MEK2/ERK2/MMP7 signaling pathways related to metastasis in different cancer cells." (PMID 37287924, 2023). "Curcumin downregulates COX-2 and EGFR expressions since PGE2 transactivates the EGFR pathway to promote cancer cell motility, indicating a cross-talk between the two pathways." (PMID 36831374, 2023). "Epidermal growth factor (EGF)-mediated activation of EGF receptors (EGFRs) has become an important target in drug development due to the implication of EGFR-mediated cellular signaling in cancer development." (PMID 36979595, 2023). "About 90% of all EGFR alterations are these two alterations, which can serve as ideal targets for cancer immunoprevention." (PMID 36875137, 2023). "Overall, DUBs are intimately related to modulating the stability of EGFR, thus conferring resistance to EGFR-TKIs in cancer cells." (PMID 36694209, 2023). "The 7D12-benzophenothiazine conjugation has demonstrated high specificity and toxicity towards EGFR-overexpressing cancer cells in vivo and in vitro, under both normal and hypoxia conditions." (PMID 38067344, 2023). "In particular, in vitro studies performed in EGFR-dependent solid tumours and/or cell cultures will be explored, thus shedding light on the interplay between EGFR and EVs production in promoting cancer progression, metastases, and resistance to therapies." (PMID 37296932, 2023). "The overexpression of EGFR is known to be involved in various cancers mediated by the stimulation of carcinogenetic processes resulting in cell proliferation, apoptosis, angiogenesis, and invasiveness through main cascades such as Ras/Raf/MAPK and PIK-3/AKT." (PMID 37513420, 2023).
cancer (continued). "Among the tumorigenesis-associated genes, KEGG analysis revealed that the upregulated genes, including SLC7A5, E2F1, HIF1A, VEGFA, and EGFR, were predominantly related to central carbon metabolism in cancer, the cell cycle, and the HIF-1 signaling pathway." (PMID 37328520, 2023). "We then used the cancer cell state map as a framework to visualize pathway activation by plotting the 25 tumors with the highest pathway activation score for EGFR, estrogen, and hypoxia." (PMID 37578979, 2023). "The molecular mechanisms of EGFR in cancer and AD are also being investigated to develop disease-modifying drugs." (PMID 37601068, 2023). "The targeting of KRAS has been extensively investigated since its discovery as an oncogene, and more earnestly after the discovery that KRAS-mutant cancers are resistant to anti-EGFR therapy." (PMID 37190303, 2023). "These EGFR aberrations promote cancer cell proliferation by activating downstream oncogenic signaling pathways." (PMID 37298389, 2023). "As one of the ERBB receptors, EGFR has been identified as an oncogene and was the first growth factor receptor to be proposed as a target for cancer therapy." (PMID 37658049, 2023). "For example, EGFR was found enriched in EGFR tyrosine kinase, cancer, PI3K-Akt signaling, relaxin signaling, foxO signaling, Rap1 signaling, MAPK signaling, JAK-STAT and calcium signaling pathways." (PMID 38196993, 2023). "Cancer-related abnormal signal transduction pathways including EGFR, FGFR, WNT, TGF-beta, and MAPK are activated during ESCC progression stages." (PMID 37553345, 2023). "Most clinical and preclinical studies involve cetuximab and panitumumab conjugated with IRdye700 (cetuximab-IRdye700 and panitumumab-IRdye700) for targeting the membrane receptor epidermal growth factor receptor (EGFR) overexpressing cancer cells." (PMID 36768976, 2023). "This upregulation leads to the removal of fucose from the EGFR protein, ultimately suppressing cancer cell growth and inducing cell death." (PMID 37601653, 2023). "Treatment with anti-EGFR cetuximab restores the chemosensitivity of tumors derived from co-injection of cancer cells and rCAFs in vivo, while the serum level of TGFα determines NACT response in HNSCC patients." (PMID 37821657, 2023). "This review provides insights into the potential roles of EGFR and EGFR inhibitors in cancer and AD and related therapeutic strategies." (PMID 37601068, 2023). "By targeting EGFR, which is commonly expressed on carcinomas, CD27xEGFR induced cancer cell-localized crosslinking and activation of CD27." (PMID 37545491, 2023). "We also discuss recent developments and the use of specific therapeutic strategies, such as multi-targeting agents and combination therapies, for overcoming cancer resistance to EGFR-specific drugs." (PMID 38201251, 2023). "Resistance mechanisms to EGFR tyrosine kinase inhibitors are a class of cancer therapies that focus on the epidermal growth factor receptor." (PMID 37571339, 2023). "Although there are conflicting reports regarding the role of EGFR in Aβ pathology, there is strong evidence that EGFR is a dual molecular target for cancer and AD." (PMID 37601068, 2023). "Upon activation of EGFR, c-Src phosphorylates CHKα at Tyr197 and Tyr333, which increases CHKα activity and, consequently, the proliferation of cancer cells." (PMID 37046844, 2023). "Under these conditions, the mathematical model predicted and resulting data have confirmed a progressive uncoupling of EGFR phosphorylation and ubiquitylation, an intrinsic weakness that appears to be exploited by cancer cells harboring EGFR overexpression." (PMID 37673340, 2023). "The Epidermal growth factor receptor (EGFR) is a receptor tyrosine kinase that, upon activation, upregulates downstream signalling cascades that initiate oncogenic processes, such as cancer cell proliferation, anti‐apoptosis, angiogenesis and invasion." (PMID 37177859, 2023).
cancer (continued). "Abnormal activation of the EGFR pathway, through mutations or overexpression of EGFR or its ligands, has been implicated in the development and progression of various types of cancer, including NSCLC, making EGFR an important target for cancer treatment." (PMID 37901797, 2023). "Major compounds extracted from ginger exert a potential anti-cancer effect by inhibiting the phosphorylation of EGFR (epidermal growth factor receptor) in various cancer types." (PMID 36768961, 2023). "MET alterations, in addition to their primary cancer driver role, can mediate resistance to other targeted therapies, such as EGFR inhibitors." (PMID 36670542, 2023). "Although the EGFR-targeted antibodies cetuximab and panitumumab have provided substantial benefits to patients with advanced cancer, their clinical efficacy is limited by intrinsic and acquired resistance." (PMID 37658049, 2023). "The over-activation of EGFR is observed in many types of cancers, including head, neck, breast, lung, colorectal, prostate, kidney, pancreas, ovary, and brain cancers." (PMID 37687164, 2023). "The elucidation of the molecular processes involved allowed us to explain the mechanism of targeted EGFR degradation and postulate an alternative vision for cancer chemotherapy." (PMID 37754201, 2023). "Several oncogenic driver mutations, e.g., epidermal growth factor receptor (EGFR; 15–20% of NSCLCs) and anaplastic lymphoma kinase (ALK; 5% of NSCLCs), have been shown to promote cell transformation and cancer growth and progression." (PMID 37543587, 2023). "EGFR is often thought of as an angiogenic and metastatic regulator for cancers, allowing more perfusion with blood to encourage proliferation and spread to distant sites." (PMID 37232831, 2023). "For example, upregulation of clathrin light-chain (CLCb) leads to an increased rate of CME; this in turn alters the trafficking of oncogenic epidermal growth factor receptor (EGFR) and promotes cancer cell migration and metastasis." (PMID 37099601, 2023). "The multifunctional delivery vector we prepared can specifically deliver a genome editing plasmid into CMCs in the blood sample of cancer patients for epidermal growth factor receptor (EGFR) knockout." (PMID 37590231, 2023). "There were significant regional differences in the prescriptions of EGFR-TKIs in Japan based on the number of coordinated designated cancer hospitals and the number of patients receiving radiotherapy alone." (PMID 36997606, 2023). "We expect this formulation to have the dual advantage of diminishing resistance development in cancer cells and eliciting ameliorating, anti-cancer effects via the inhibition of epidermal growth factor receptor (EGFR) and damage to DNA." (PMID 37259356, 2023). "EGFR overexpression has been considered a poor prognostic factor in cancers of the head and neck, esophagus, ovary, uterine cervix, and bladder through primary-level studies." (PMID 37569265, 2023). "The obtained 7D12-NK92MI exhibited high targeting and affinity to EGFR-positive cancer cells, resulting in good tissue penetration and enhanced secretion of cytotoxic cytokines such as enzyme B, IL-2, and IFN-γ." (PMID 37514008, 2023). "In renal distal convoluted tubule (DCT), EGF increases TRPM6 activity and surface expression, while in cancer patients receiving anti-EGFR treatment, serum level of Mg2+ was significantly decreased." (PMID 36818331, 2023). "Due to the limitations of conventional chemotherapy, such as high toxicity and low tumorsensitivity, EGFR has emerged as a crucial therapeutic target for cancer treatment." (PMID 37808374, 2023). "In cancer, EGFR inhibitors target cell proliferation and angiogenesis, and studies in AD mouse models have shown that EGFR inhibitors can attenuate amyloid-beta (Aβ) pathology and improve cognitive function." (PMID 37601068, 2023).
cancer (continued). "Previously, we showed that the therapeutic antibody nimotuzumab can be repurposed as a PET or optical-imaging probe for EGFR positive cancers in mice." (PMID 37419997, 2023). "drug category revealed that drugs with similar targets tend to be clustered together, and drugs targeting ErbB2, 3, and 4 were more potent in cancer cell lines with high ErbB2 expression as compared with drugs targeting EGFR (ErbB1) alone." (PMID 37508418, 2023). "The inhibition of EGFR overexpression is considered a crucial strategy in current anti-cancer research." (PMID 38005329, 2023). "Firstly, SEMA3E, through its receptor, PlexinD1, promotes the proliferation, migration and invasion of cancer cells through its ability to activate the oncogenic signalling of epidermal growth factor receptor (EGFR) and HER-2." (PMID 37685898, 2023). "Later, EGFR expression level was selected as a marker for predicting tumor grade, cancer progression, and early relapse of cancer." (PMID 38273823, 2023). "In recent years, many agents, TKIs, and monoclonal antibodies have been developed and used in the clinical treatment of different cancer types with the goal of inhibiting the signaling pathways of EGFR." (PMID 37446288, 2023). "The Hippo pathway can also interact with the epidermal growth factor receptor (EGFR) pathway, thereby regulating cancer cell invasion." (PMID 37190141, 2023). "This study examines the potential of Cannabis sativa L. plants to be repurposed as therapeutic agents for cancer treatment through designing of hybrid Epidermal growth factor receptor tyrosine kinase inhibitors (EGFR-TKIs)." (PMID 37128337, 2023). "In photo-immunoconjugate nanoparticles (PIC-NP), photosensitizers in cancer cells were dramatically boosted, as was light-activated cytotoxicity in U87 cells overexpressing EGFR." (PMID 38201528, 2023). "A recent report showed that pharmacological targeting of PARP increases the sensitivity of cancer cells to EGFR inhibition, but the therapeutic value of this combination has not been fully determined." (PMID 37441599, 2023). "Currently reported underlying mechanisms of LAMC2-induced cancer cell progression and metastasis include regulation of integrin B1-, ZEB1, and Snail expression, as well as activation of AKT1 and EGFR." (PMID 37542131, 2023). "EGFR signaling is a mechanism of autonomous proliferation involved in the pathogenesis of many types of cancer." (PMID 37114127, 2023). "The extracellular domain-targeting ASO treatment reduced EGFR protein expression in both Huh-7 and U87-MG cancer cells." (PMID 38137520, 2023). "For example, the epidermal growth factor receptor (EGFR) pathway is key in the development and progression of many cancers, including CRC." (PMID 36900187, 2023). "EGFR has the advantage of being a well-established oncogenic TAA whose overexpression has been reported in numerous cancers, including some responsive to both anti-EGFR and anti-PD1/PDL1 therapies." (PMID 37189383, 2023). "Overexpression or abnormal activation of the epidermal growth factor receptor (EGFR) is observed in many human cancers 1-3." (PMID 37441599, 2023). "It is becoming clear that EGFR trafficking has implications in different types of cancer and that the development of resistance to TKIs is related to altered EGFR trafficking." (PMID 37752992, 2023). "These reasons are sufficient to multiply studies and researches to develop and to screen new generations of EGFR-TKIs for an effective cancer treatment." (PMID 37128337, 2023). "EGFR is a transmembrane glycoprotein that is overexpressed in several cancers, especially NSCLC, and it promotes cell proliferation, invasion, and chemoresistance." (PMID 36810440, 2023).